IL6 (interleukin 6)
Diseases named in the same sentence as IL6 in open-access papers (continued):
Sharing a sentence is not in itself a finding about the gene and the disease.
breast tumor (continued). "Canonical Pathway Analysis of DEGs identified an enrichment in GP6, PKCθ, TLR, NF-ƙB signaling and dendritic cell maturation biological processes in NK cell-infiltrated breast tumors, which also showed negative scores for IL-6 signaling-related genes." (PMID 38167224, 2024). "Specifically, IL-6, IL-11, their receptors and downstream transcription factor STAT3, are known to be highly expressed in breast cancer, and the role of cytokine-induced STAT3 signaling in the breast tumor microenvironment is multifaceted." (PMID 35053592, 2022). "In our analysis of the TCGA breast tumor cohort, we observed significant positive correlations between TREM1 expression and the expression of TREM-1 target cytokines (IL1B, IL8, IL6 and CCL2) and markers of MDSCs and TAMs (CD11B/ITGAM, OLR1, CD14 and CD206/MRC1)." (PMID 34956864, 2021). "In addition, we also examined the levels of proinflammatory cytokines such as IL12/IL6, expressed in circulating macrophages (CD68), which also accumulate in a breast tumor microenvironment." (PMID 33414685, 2020). "Non-canonical Notch signaling has been shown to activate IL-6/JAK/STAT signaling in breast tumor cells in a NF-κB dependent manner." (PMID 30564555, 2018). "Two well-known ligands for AHR (TCDD and BaP) induced mRNA expression of IL1B and IL6 in an ERα-negative breast tumor cell line." (PMID 29320557, 2018). "For instance, we wonder if there could be a potential prognostic value of the cytokines IL-6, GRO and MCP-2 or if they could be used as additional markers for breast tumor stage." (PMID 30123423, 2018). "Secretion of multiple cytokines including IL-6, IL-12, IL-1β and TNF-α from DCs was measured by ELISA Kit after transwell co-culture (diffusion model) or direct co-culture of immature DCs with the ablated breast tumor cells (cell contacting model) for 24 h." (PMID 30583459, 2018). "Finally, lower levels of several pro-inflammatory cytokines (IL1B, IL10, IL12, IL6, IL8, TNF), NK cell metagenes (NCR1, XCL1), cytolytic enzymes (GZMA, GZMB, PRF) and type I IFN-induced genes were also observed in IL-1R8 high breast tumors." (PMID 28533483, 2017). "Importantly, IL-6 can induce EMT through the STAT3 signaling, and its level increases with higher breast tumor grade and correlates with metastasis and poor patient survival." (PMID 29088851, 2017). "Our study has uncovered an IL-6-Dub3-Slug/Twist signaling axis during EMT and suggests potential approaches that could target Dub3 to prevent metastatic breast tumor." (PMID 29088851, 2017). "IL-6 and VEGF are two key factors overexpressed in breast tumors." (PMID 27283985, 2016). "Using this protein in prevention of poisoning (e.g. in chemical warfare) may have serious implications, such as breast tumor development, should at the time of high PON1 levels, IL6 levels also be raised." (PMID 21711799, 2011). "TNF-α expression and IL8, IL1A and IL6 expression were only correlated in ER-negative, but not in ER-positive breast tumors." (PMID 21754991, 2011). "However, it has been proved that Fe not only works fundamentally in many pathophysiological functions but also participates in the occurrence of breast tumors by interfering with signalings, such as VEGF, ROS, MAPK, and IL-6/JAK2/STAT3 signaling in animal models." (PMID 35782923, 2022). "Based on this, we hypothesized that in normal condition, DUOX1 could be involved in IL-6 and IL-8 secretion after genotoxic stress in mammary epithelial cells; however, the physiological relevance of the lower DUOX1 expression found in breast tumor remains to be elucidated." (PMID 29849884, 2018). "Our results showed that The mechanisms of YHD inhibit 4T1 breast tumor growth may be related to downregulating the expression of iNOS and ARG-1, negatively regulating the Janus kinase/STAT3 (JAK/STAT3) pathway by repressing the expression of IL-6 and TGF-β." (PMID 30581487, 2018).
breast tumor (continued). "On the other hand, in the hypoxic breast tumor microenvironment, HIF-1α triggers Notch-3 up-regulation toward the decrease of IL-6 levels and the inhibition of the CSCs population, whereas the gamma secretase inhibitors MK-0752 and RO4929097 increase the CSCs population in an IL-6 dependent manner." (PMID 29996493, 2018). "Our study indicates that the range of cytokines carried by breast tumor cells (stromal and epithelial cells) under PRP supplementation and in co-culture with HUVEC was tumor-subtype and cancer cell-type specific; these cytokines include IL-8, IL-6, TNF-α, and VEGF but are not limited to these ones." (PMID 28187434, 2017). "However, we did not observe any significant changes in VEGF or IL-6 expression in MDA-MB-231 breast tumor xenografts or cells." (PMID 27283985, 2016). "Also, IL6 and IL8 appear to be important in breast tumor growth." (PMID 24265713, 2013). "In this respect, it was found also that fibroblast-derived SASP induced EMT in non-aggressive breast tumor cells, with direct roles of CXCL8 + IL-6 in promoting tumor cell invasiveness." (PMID 32582148, 2020).
dengue (143 papers, 2008 to 2026). "The inability to downregulate innate cytokines, particularly TNF‐α, IL‐6, and IP‐10, during the late phase of illness has been associated with delayed resolution of serum inflammatory mediators in patients with severe dengue." (PMID 41488232, 2026). "The literature on IL-6 in dengue is less robust than that for ferritin, but several groups have also found an association between elevated IL-6 and disease severity." (PMID 38536887, 2024). "The elevation of pro-inflammatory cytokines especially TNF-⍺ and IL-6 are a major factor to cause the severe dengue disease, as these cytokines attract and facilitate monocytes infiltration at the site of DENV deposition or infection." (PMID 36658277, 2023). "IL-1β and IL-6 are both associated with the severity of dengue fever, promoting the activation of IL-1β and leading to tissue damage and vascular leakage." (PMID 37024713, 2023). "Eventually elevated levels of inflammatory cytokines (especially TNF-α and IL-6) potentiate cascade of events that culminate in vascular permeability and haemorrhage, which is the leading cause of severe dengue illness." (PMID 36658277, 2023). "Cytokines including TNF- α, IFN- γ, IL-1β, IL-2, IL-6 and IL-10 have been linked to the pathogenesis of other viral hemorrhagic diseases, such as dengue, and Ebola." (PMID 34793450, 2021). "In DENV-2 genotype, T164S mutation in NS1 protein ascertains the fact that mutation in dengue protein can enhance clinical severity, as well as increased Th1 response—IL-6, IFNγ, and TNFα—in in vivo and in vitro experimental model." (PMID 34447698, 2021). "Several lines of evidence indicate that high IL-6 levels are correlated with bacterial sepsis, severe malaria, severe dengue, and increased risk of dengue mortality." (PMID 33072673, 2020). "IFN-γ-mediated immune responses are described as crucial for viral clearance in DENV-infected mice, both for the early and late stages of infection, while TNF and IL-6 are associated with severe dengue in mice and humans." (PMID 35047876, 2020). "Consistent with dengue-associated cytokine profiles reported in humans, increased IL-6, IL-8, TNF-α and MCP-1 levels were detected in most groups after challenge." (PMID 31009499, 2019). "A number of pro-inflammatory cytokines in particular have been implicated in severe dengue, including TNFα, IFNγ, IL-18, IL-1β, and IL-6." (PMID 30557313, 2018). "IL-6 has been shown by several groups to be elevated during dengue illness and associated with severe forms of the disease." (PMID 27459266, 2016). "Proinflammatory cytokines such as TNFα, IFNγ, and IL-6 have been associated with severe secondary dengue disease in several studies." (PMID 22816004, 2012). "Increased IL-6 has been associated with severe dengue in many studies (74, –, 76), and results here suggest modulating Vav does not compromise control of DENV replication but may not benefit control of IL-6 production." (PMID 38054722, 2024). "Interestingly, sensing of prM-DENV2 triggered the production of TNF-α, IL-1β, and IL-6 cytokines which are usually associated with EC activation and damage during severe dengue." (PMID 36240261, 2022). "The ability of FCPLJ to decrease the proinflammatory cytokines could possibly reduce the severity of dengue, as IL-6, MCP-1, IL-1 beta and MIP-1 beta have been associated with severe dengue infection." (PMID 33919457, 2021). "Some show IL-6 levels to be associated with Dengue disease severity." (PMID 30112159, 2018). "IL-6 has been implicated in the pathogenesis of severe cases of dengue as this cytokine enhances the production of anti-platelet or anti-endothelial cell auto-antibodies, as well as the induction of tissue plasminogen activator, leading to increased risk for bleeding." (PMID 26271921, 2015). "Another cytokine produced is IL-6, which may be associated with severe dengue manifestations." (PMID 41417343, 2025).
dengue (continued). "The overproduced IL-6 might enhance production of anti-platelet or anti-endothelial cell autoantibodies, elevated levels of tPA, and deficiency in coagulation, which may explain higher occurrence levels of DVG_969_1022 in severe dengue patients." (PMID 35223554, 2022). "In addition, IL-6, which belongs to the pathological immunological profile and was found at significantly higher levels in DwWS/SD patients, has been associated with severe dengue in several studies." (PMID 34578370, 2021). "Additionally, a close association between cytokine imbalance and SOCS1/3 observed in patients with a severe dengue infection suggested that the combined analysis of SOCS1/3, IL-10, and IL-6 expression levels could identify at-risk patients for severe dengue." (PMID 32120897, 2020). "However, most severe dengue patients had lower levels of interferons and Th1 cytokines and increased levels of secreted factors such as IL-6, IL-8 and IL-10 that could potentially cause leakage in blood capillaries." (PMID 26982706, 2016). "On the other hand, IL‐6, as a potent inflammatory cytokine, is widely reported as a biomarker for dengue severity." (PMID 41488232, 2026). "Significantly higher levels of serum IL-6 and IFN-γ are observed in severe dengue patients, and elevated IL-6 levels are associated with dengue mortality." (PMID 40006981, 2025). "Survivors of dengue shock and septic shock had persistently elevated ferritin and IL-6 at all post-discharge timepoints when compared with healthy controls (P < .01 for all comparisons)." (PMID 41180006, 2025). "This demonstrates heterologous viral imprinting, creating a “hybrid” dengue phenotype combining DHF’s acute vascular pathology with long COVID’s chronic inflammation through Th2 skewing and IL-6-linked ADE." (PMID 41583452, 2025). "Elevated IL-6/CRP corroborates the coagulation–proinflammatory interplay in the immune response in dengue pathogenesis." (PMID 41583452, 2025). "Evidence is accumulating that there is a complex interplay between IL-6 signaling and the vascular endothelium in disorders characterized by cytokine storms such as dengue." (PMID 40006981, 2025). "In severe dengue, the immune system’s response produces cytokines such as interleukin 6 (IL-6) and tumor necrosis factor alpha (TNF-α), which increase BBB permeability and contribute to vasogenic edema." (PMID 40600037, 2025). "The possibility of immunotherapy against severe dengue by targeting IL-6 or IL17A should be carefully considered." (PMID 37939119, 2023). "Resistin is mainly produced by monocytes, macrophages and other leucocytes and its production is shown to be stimulated by lipopolysaccharide (LPS) and cytokines such as IL-6, TNFα and IL-1β, which are all shown to be elevated during early illness in dengue." (PMID 37676889, 2023). "IgG-mediated ADE significantly increases production of pro-inflammatory cytokines including type I interferon, IL-6, MIP-1α, and TNF, which are associated with dengue symptoms and development of pathogenesis." (PMID 37639455, 2023). "In our study, it was shown that the plasma levels of IL-6 of dengue patients had a positive correlation with the D-dimer levels." (PMID 34578370, 2021). "The upregulation of IL-6 and CXCL-10 expression had been reported previously as being associated with liver dysfunction in dengue patients." (PMID 34959637, 2021). "The dengue patients with mucosal bleeding (n = 22) presented significantly increased plasma levels of IL-6 (median: 20 pg/mL; IQR: 11.4–38.8; p = 0.005) and IL-10 (median: 4.1 pg/mL; IQR: 2.7–11.8; p = 0.028) compared to those without mucosal bleeding." (PMID 34578370, 2021). "The immunomodulatory potential of C. papaya leaf has been demonstrated clinically, where the reduction of proinflammatory cytokine level, such as IL-6, was observed in severe thrombocytopenic dengue patients treated with C. papaya leaf extract (Caripill)." (PMID 33919457, 2021).
dengue (continued). "Previously our lab demonstrated that high levels of IL6 were observed in severe dengue patients as compared to HD." (PMID 33436908, 2021). "Among the coagulation mediators analyzed, TF and TFPI together with IL-6 formed the second pattern identified in the dengue patients through PCA analysis." (PMID 34578370, 2021). "Lethal dengue disease is characterized by the robust induction of cytokines and chemokines in mouse serum, such as interleukin (IL)-6, IL-10, and interferon (IFN)-γ, showing a high correlation with infectious disease progression." (PMID 33072626, 2020). "Our finding is consistent with other studies in association of IL-6, IL-8, IL-15, MCP-1, and TNF-α in dengue fever." (PMID 30626045, 2019). "Dengue virus (DENV) infection induces TNFα and IL-6 production in dengue patients, and serum TNFα is positively correlated with disease progression." (PMID 29668683, 2018). "We investigated the association of the cytokines TNFα, IL-6 and CXCL10 in patients with differing Dengue disease severity as compared with healthy controls." (PMID 30112159, 2018). "Dengue virus-induced inflammatory cytokines such as TNF-α, IL-6, and IL-8 are critical in the pathogenesis of dengue fever and dengue hemorrhagic fever." (PMID 30186771, 2018). "It has been reported that secretion of both IL-6 and GM-CSF is significantly enhanced in patients with severe dengue." (PMID 29976871, 2018). "When serum IL-6 levels were compared between HC and different Dengue groups, it was found that IL-6 levels were similar." (PMID 30112159, 2018). "IL-6 was chosen as the target gene as a marked upregulation of the gene has been reported in dengue cases." (PMID 30071880, 2018). "Our results show variation between IL-6 levels and increase in TNFα and CXCL10 serum levels to be associated with Dengue severity." (PMID 30112159, 2018). "High concentrations of IL-6 were found in dengue patients in our study, and this is consistent with most studies." (PMID 28827898, 2017). "A higher concentration of IL-6 was found in dengue patients compared to the control group (110.3 ± 37.88 pg/ml versus 62.48 ± 2.47 pg/ml; P < 0.001)." (PMID 28827898, 2017). "A previous report has shown high levels of IL-6, but not IL-12 or Foxp3+ (a marker of regulatory T-cells) cells, in dengue infected liver sections suggesting a critical role for IL-6 in dengue pathogenesis." (PMID 26982706, 2016). "By both univariate and multivariate analysis, we show that the most prominent features of severe dengue are lower type I and type II interferons, IL-7, sCD40L and increased production of IL-6, IL-8, IL-10 and VEGF." (PMID 26982706, 2016). "Together with other chemotactic effectors (CXCL9/10/11) and immune cell response-modulating cytokines (IL-6, IL-7 and BAFF), RANTES has been associated with immune enhancement and increased vascular permeability following dengue virus infection." (PMID 28006034, 2016). "Severe dengue cases had low Th1 cytokines and a concurrent increase in the inflammatory mediators such as IL-6, IL-8 and IL-10." (PMID 26982706, 2016). "Severe dengue has been proposed to be an outcome of exaggerated immune response and pathology resulting from the onslaught of inflammatory mediators such as IL-6, IL-8, IL-10 and TNF-α." (PMID 26982706, 2016). "Another recent report revealed that, in fact, a disturbance in the balance between inflammatory (IL-6 and IL-8) and anti-inflammatory (IL-10) cytokines, would characterize possible mechanisms related to the occurrence of hemorrhagic manifestations in dengue." (PMID 28006034, 2016). "IL-6 expression was slightly down-regulated by dengue envelope protein (296 pg/ml) and NS3 protein (297 pg/ml) compared to His-tag-treated PBMC (346 pg/ml)." (PMID 26226614, 2015). "Similar to monocytes, IL-6 and TNF-α are implicated in both the protection and immunopathogenesis of dengue virus infection." (PMID 26226614, 2015).